LEP (leptin)
Diseases named in the same sentence as LEP in open-access papers (continued):
Sharing a sentence is not in itself a finding about the gene and the disease.
Obesity (continued). "Obesity, the main risk factor for metabolic syndrome, is affected by genetic variations in leptin (LEP), leptin receptor (LEP), and melanocortin 4 receptor (MC4R)." (PMID 40430848, 2025). "Leptin has immunomodulatory functions and when associated with obesity, it can provoke a systemic inflammatory state that can promote the development of autoimmune diseases." (PMID 40218202, 2025). "Dysregulation of leptin signaling (leptin resistance) and increased serum TG levels are associated with obesity-related disorders and insulin resistance." (PMID 40968148, 2025). "Disruption of insulin–leptin crosstalk contributes to central insulin and leptin resistance, a hallmark of obesity and type 2 diabetes." (PMID 41409607, 2025). "Congenital deficiency of leptin in mice (ob/ob mouse) and humans results in hyperphagia, extreme obesity and infertility." (PMID 40616697, 2025). "Recent studies have highlighted the management of leptin replacement therapy in monogenic obesity, identifying two LEP variants with opposing functional effects." (PMID 40415699, 2025). "Hippocampal transcriptomic analysis reveals disruption in pathways linked to obesity and cognitive decline, which is mitigated by perinatal leptin supplementation." (PMID 40944384, 2025). "In females, metabolic abnormalities such as obesity and elevated insulin and leptin are associated with acyclicity." (PMID 40646763, 2025). "For example, obesity related to congenital leptin deficiency has been successfully treated with recombinant leptin." (PMID 40564803, 2025). "Research shows that Bacteroidetes can convert polysaccharides into short-chain fatty acids, stimulate leptin secretion, enhance lipid excretion, and ameliorate conditions associated with obesity and hyperlipidemia." (PMID 40248428, 2025). "Obesity was independently associated with elevated serum leptin levels among female shift workers, suggesting that excess adiposity remains a key determinant of leptin dysregulation in this population." (PMID 41439942, 2025). "Leptin, an adipocyte-derived hormone, plays a pivotal role during breastfeeding by regulating energy homeostasis and influencing susceptibility to obesity later in life." (PMID 40290039, 2025). "The mechanisms underlying obesity-related hypertension include insulin- and leptin-mediated activation of the sympathetic nervous system, which in turn stimulates the renin–angiotensin–aldosterone system (RAAS) and promotes renal sodium retention." (PMID 41150735, 2025). "Over the past several decades, extensive research has implicated leptin as a key regulator of energy homeostasis and a central player in the pathophysiology of obesity." (PMID 41251447, 2025). "The db/db mouse is an excellent model for severe obesity-related metabolic disease, but it is characterized by leptin resistance by definition due to leptin receptor deficiency." (PMID 40639664, 2025). "Such dysregulation leads to leptin resistance—a hallmark of obesity—where, despite elevated leptin levels, hypothalamic receptors fail to respond adequately, promoting excessive caloric intake." (PMID 41010468, 2025). "Impaired leptin signaling, which is a hallmark of obesity, is linked to an increase in amyloid-β accumulation and tau hyperphosphorylation, both of which are associated with AD pathology." (PMID 41515969, 2025). "Ongoing research continues to investigate the molecular and cellular mechanisms driving leptin resistance, with the goal of identifying new therapeutic strategies to combat obesity and associated complications." (PMID 41251447, 2025). "Herein, we confirmed the anti-hyperglycemic effect of SGLT2i in a genetic model of obesity represented by the ob/ob leptin-deficient mice, but we reported a reduction of blood glucose levels after treatment also in wild-type lean animals." (PMID 40059147, 2025).
Obesity (continued). "On the other hand, the appetite controller hormone leptin, a molecule encoded by the Ob gene whose circulating levels are elevated in individuals with obesity, has been demonstrated to play a significant role in BC biology." (PMID 40523654, 2025). "Obesity also causes dysregulation of adipokine production, with increased leptin levels and decreased adiponectin levels." (PMID 39906505, 2025). "Our findings are key to understanding the initial biochemical alterations that occur in kidney tubules at the early stages of obesity associated nephropathy in ob/ob mice with leptin deficiency." (PMID 41213922, 2025). "Recessive forms of severe obesity were identified, caused by homozygous or compound heterozygous mutations in the following genes: LEP (leptin), LEPR (leptin receptor), BBS1 and BBS10 (Bardet–Biedl syndrome), and POMC (pro-opiomelanocortin)." (PMID 40149731, 2025). "Mutations in genes implicated in the leptin–melanocortin pathway are found in 2–5% of patients with monogenic obesity." (PMID 40428410, 2025). "Leptin resistance is commonly associated with obesity and accelerated aging, while leptin sensitivity is linked to metabolic health and longevity." (PMID 40275190, 2025). "Leptin demonstrated the strongest association with obesity and metabolic disturbances, supporting its potential as a biomarker for identifying metabolic risk in PCOS." (PMID 40792318, 2025). "Obesity is associated with elevated circulating leptin, a pro-inflammatory peptide hormone involved in energy homeostasis." (PMID 40755647, 2025). "Fat tissue in obesity is deficient in adiponectin, an immune-modulating hormone, and enriched in leptin, which contributes to immune dysregulation." (PMID 40005064, 2025). "Obesity-associated adipokines adiponectin and leptin jointly mediate the inflammatory injury and carcinogenic progression of GERD." (PMID 41384250, 2025). "Like metabolic factors, adiponectin and leptin are also associated with increasing obesity and other diseases." (PMID 40770283, 2025). "Central insulin and leptin resistance, hypothalamic inflammation, and impaired brainstem autonomic control are implicated in the pathogenesis of obesity and T2DM." (PMID 41409607, 2025). "In parallel, leptin—an adiposity signal often elevated in obesity—has been linked to reward-related eating and putative leptin resistance." (PMID 41356005, 2025). "In this regard, besides being analyzed for its association with obesity, the association of leptin levels with lipid profiles has been extensively studied in adults and children, describing an association with an adverse lipid profile." (PMID 41465332, 2025). "The increased ghrelin/leptin ratio is an independent risk factor for the development of obesity and T2DM." (PMID 38778593, 2025). "These contrasting roles of leptin and adiponectin highlight their distinct contributions to bone metabolism and their interplay with pathological states like obesity and estrogen deficiency." (PMID 39940349, 2025). "Given that adipokines such as adiponectin and leptin are secreted by adipose tissue in obesity, which leads to inflammation, weight loss following a yogic diet and lifestyle changes lessens inflammation in adipose tissue and increases insulin sensitivity." (PMID 40216734, 2025). "Collectively, these results demonstrate that deficiency of LGR4 in neurons protects against diet-induced obesity by decreasing food intake and increasing energy expenditure through improved leptin sensitivity." (PMID 40069508, 2025). "There are several monogenetic and polygenetic experimental models of obesity: some notable examples include leptin-deficient mice (ob/ob), leptin-receptor deficient mice (db/db) and the New Zealand obese mouse strain (NZO)." (PMID 40837095, 2025). "Leptin, one of the most well-characterized adipokines, has significant implications in atherosclerotic complications associated with obesity." (PMID 40940776, 2025).
Obesity (continued). "Based on the widely accepted view that WAT secretes a diverse array of peptide and steroid hormones, including leptin, cytokines, and adiponectin, it is evident that obesity-induced adipokine dysregulation is closely linked to subcutaneous fat." (PMID 40431382, 2025). "The parents of 134 of these children were also enrolled to examine the relationship of leptin and leptin receptor polymorphisms with obesity." (PMID 40559461, 2025). "Alterations in the gut microbiota have been implicated in the development of obesity and its related metabolic disorders, with evidence suggesting that modulating the gut microbiota can influence leptin sensitivity and metabolic outcomes." (PMID 40095902, 2025). "The report confirmed a homozygous mutation in the LEP gene variant NM_000230:c.350G > T (NP_000221 1:p.Cys117Phe), indicating congenital leptin deficiency as the cause of monogenic obesity." (PMID 41013830, 2025). "In contrast, monogenic obesity, caused by a single, rare mutation in genes like LEP, LEPR, POMC, or MC4R, accounts for less than 1% of obesity cases." (PMID 40564803, 2025). "Consistently, DIO mice show decreased hypothalamic LepR mRNA despite elevated leptin levels, suggesting that diminished receptor responsiveness contributes to obesity-associated leptin resistance." (PMID 41516046, 2025). "The first identified cause of monogenic obesity was a deficiency in leptin, a hormone that regulates food intake and basal metabolism at the central level." (PMID 40019662, 2025). "Monogenic obesity is one of the rare causes of obesity, with leptin deficiency due to LEP gene mutation being one of them." (PMID 41013830, 2025). "Leptin resistance or leptin signaling deficiency observed in obesity leads to increased cardiovascular disease risk through a plethora of mechanisms." (PMID 39812779, 2025). "A potential relationship between obesity and the onset of psoriasis is underscored by elevated leptin levels, which are linked to altered regulatory T cell (Treg) activity and disruption of the Treg/Th17 cell balance." (PMID 40893809, 2025). "Identifying non-AgRP neuronal subsets that are responsible for hyperphagia and obesity — but are insufficient to drive hyperglycemia — in leptin-deficient states is a priority for future research." (PMID 40371641, 2025). "Syndromic obesity is part of a common spectrum of hypothalamic pathologies characterized by severe early onset obesity caused by dysfunction of the leptin–melanocortin pathway that has a pivotal role in satiety/appetite regulation and in energy expenditure." (PMID 39940349, 2025). "Studies in vivo and in vitro have revealed that Lnc-leptin regulates leptin expression, and that dysregulation of this process is significantly linked to obesity." (PMID 40941416, 2025). "The secretion of leptin, a hormone associated with obesity, and leptin has been shown to promote airway inflammation and is associated with increased asthma risk and severity." (PMID 40998975, 2025). "Higher levels of salivary leptin were associated with obesity in 10- to 12-year-old Kuwaitis in one paper rated as having a high value when waist circumference was considered." (PMID 40565251, 2025). "Leptin, a key cytokine produced by adipose tissue, offers a more direct insight into obesity-related cardiovascular risk." (PMID 40362168, 2025). "The interest of the scientific community in studying the pathobiology of leptin was first triggered by observational and mechanistic studies reporting an association between leptin levels with adiposity and other obesity-related conditions." (PMID 40001498, 2025). "Given the significant role of leptin in regulating energy homeostasis, the influence of polymorphisms in the leptin gene on obesity and leptin plasma levels has been extensively analyzed in adults and children." (PMID 41465332, 2025).
Obesity (continued). "Pathophysiologically, obesity is associated with hormonal imbalances, including elevated leptin and insulin resistance (IR), along with dysregulated adipokine production, such as increased TNF-α and IL-6 from hypertrophic adipose tissue." (PMID 40959347, 2025). "Numerous studies have established the association of increased leptin with increased obesity in Mexican populations." (PMID 40362681, 2025). "GNPDA2 is linked to lipid metabolism and obesity, with sleep duration influencing genetic susceptibility to obesity through the leptin pathway." (PMID 40024983, 2025). "Monogenic obesity is caused by mutations predominantly in the leptin-melanocortin system, such as LEP, LEPR, POMC, and MC4R genes." (PMID 40636093, 2025). "Dysregulation of adipokine athways related to leptin and Asignaling is strongly implicated in obesity, T2D, and lipid metabolism disorders." (PMID 40692591, 2025). "Administration of ANC to high-fat-fed mice also showed numerous changes in obesity-associated indices, including improved β-cell functions as well as fasting blood glucose and leptin concentrations." (PMID 41585869, 2025). "High levels of leptin, a signature of obesity, have been recognised as a significant risk factor and an important prognostic marker in CC, impacting on cell behaviour including proliferation, apoptosis or migration." (PMID 40268791, 2025). "Under physiological conditions, leptin activates OXT-producing neurons in the paraventricular nucleus; prenatal nutrient deprivation can disrupt this interaction, promoting leptin resistance and increasing long-term risk of obesity." (PMID 41614746, 2025). "Collectively, these findings indicate that leptin resistance-associated obesity and diabetes can accelerate tau pathology in vivo." (PMID 41516046, 2025). "Gipr knockout mice fed a HFD show protection against obesity and insulin resistance even on a hyperphagic leptin-deficient background." (PMID 40166681, 2025). "Elevated leptin levels observed in obesity are often associated with a simultaneous decrease in sOB-R levels, resulting in increased FLI values." (PMID 40152811, 2025). "Various proinflammatory markers that are elevated in obesity, along with adipocytokines such as leptin and adiponectin, have been linked to the experience of migraine pain." (PMID 41278056, 2025). "Impairments in memory consolidation are linked to disrupted synthesis of neuropeptide Y in the hypothalamus, caused by an imbalance of the neurotransmitters ghrelin and leptin, leading to obesity." (PMID 41465437, 2025). "Interleukin-6 (IL-6) is a key pro-inflammatory cytokine implicated in obesity, insulin resistance, and atherosclerosis, while leptin is an adipokine secreted by adipose tissue that bridges energy homeostasis with immune function." (PMID 41384023, 2025). "In obesity-associated lung conditions, leptin is believed to be proinflammatory while adiponectin is anti-inflammatory in nature." (PMID 40118456, 2025). "Leptin signaling plays a pivotal role in the regulation of appetite and body weight and disruption of leptin or its receptor causes severe obesity in mice and humans." (PMID 39149290, 2025). "Increased plasma leptin concentration has consistently been associated with obesity, while decreased plasma adiponectin concentrations have been observed." (PMID 40346913, 2025). "Animal experimentation has demonstrated that leptin plays a pivotal role in the development of obesity-associated OA, though its function is restricted in the absence of an inflammatory background associated with obesity." (PMID 40964689, 2025). "Due to the limited evidence in literature, it is challenging to establish a more accurate prevalence rate of monogenic obesity due to LEP gene deficiency." (PMID 41013830, 2025). "Decreased sensitivity to leptin (leptin resistance) is thought to be one of the main causes of obesity." (PMID 41155431, 2025).
Obesity (continued). "Lastly, our ROC analysis demonstrated that leptin had the highest diagnostic accuracy for predicting obesity in PCOS (AUC=0.85, 95% CI: 0.79-0.91, p<0.001), followed by adiponectin (AUC=0.77, p=0.004) and resistin (AUC=0.73, p=0.015)." (PMID 40792318, 2025). "In obesity, leptin resistance and ghrelin dysregulation are associated with pro-inflammatory responses and the chronic sub-inflammatory state observed in obesity." (PMID 40137085, 2025). "Certain adipokines, i.e., leptin and adiponectin, have been linked to both the propagation of obesity and development of obesity‐related complications." (PMID 39152660, 2025). "As a result, the findings of our study are specific to individuals with obesity—a condition often associated with leptin resistance—limiting their applicability to the broader population." (PMID 39934931, 2025). "In particular, leptin deficiency was associated with the development of severe obesity in mice, and the genes encoding leptin and the leptin receptor (LEPR) were further identified and cloned." (PMID 40689079, 2025). "The influence of leptin on SM mass and function and other aspects of metabolic regulation (including appetite control) is complicated in humans by the association of obesity with leptin resistance." (PMID 39997710, 2025). "Leptin is one of the key adipokines associated with obesity and has been shown to exert pro-inflammatory effects." (PMID 41154857, 2025). "Monogenic obesity, typically caused by leptin–melanocortin pathway gene defects (e.g., LEP, LEPR, POMC, MC4R), leads to severe early-onset hyperphagia and weight gain." (PMID 40868047, 2025). "Leptin is a hormone derived from the obesity gene discovered through research on the pathogenic gene in genetically obese mice." (PMID 39897330, 2025). "Islets from mice with obesity from a high-fat diet or leptin deficiency and animals given a single dose of streptozotocin (STZ) had higher islet content of GLP-1 than controls." (PMID 40971442, 2025). "On a similar note, a state of obesity by itself is a risk factor of periodontal destruction and it increases the release of adipokines (such as leptin and resistin) and destructive inflammatory cytokines such as IL-6." (PMID 41396032, 2025). "Short sleep duration is also associated with increased ghrelin/leptin ratio and is an independent risk factor for the development of obesity and T2DM." (PMID 38778593, 2025). "Following the administration of the barley sprout diet, a reduction in the concentration of the obesity-associated protein leptin was observed." (PMID 40142488, 2025). "In mice, genetic disruption of Sh2b1 also results in obesity, insulin resistance, type-2 diabetes, severe leptin resistance, and metabolic dysfunction-associated steatotic liver disease." (PMID 39948378, 2025). "It is likely that needle therapy affects biochemical markers associated with obesity, including obesity-related peptides (e.g., leptin and ghrelin), insulin resistance, and inflammatory markers." (PMID 40316554, 2025). "Obesity is also associated with decreased adiponectin, increased leptin, increased insulin resistance, and a pro-inflammatory state, which synergistically promotes carcinogenesis." (PMID 40722646, 2025). "Leptin and adiponectin levels were measured to assess the hormonal regulation of obesity and metabolic balance associated with HFD feeding." (PMID 40535914, 2025). "Key genes implicated in monogenic obesity include those involved in the leptin-melanocortin signaling pathway, such as MC4R, LEPR, PCSK1, and POMC, among others." (PMID 40281302, 2025). "“Thrifty genes”, including those linked to leptin, play a crucial role in obesity and metabolic diseases, with mutations leading to leptin resistance (LR) and obesity." (PMID 41321496, 2025). "Within the obesity subgroup, higher leptin levels were paradoxically associated with lower BMI (β = −2.33; p = 0.016)." (PMID 41423640, 2025).